ACVRL1 (activin A receptor like type 1)
Diseases named in the same sentence as ACVRL1 in open-access papers (continued):
Sharing a sentence is not in itself a finding about the gene and the disease.
tumor (continued). "Indeed, pharmacological inhibitors of two genes (ACVRL1 and AXL) are currently the subject of clinical trials in a range of tumour types as prospective anti-angiogenic therapeutics." (PMID 29915322, 2018). "In agreement with our previous reports, ablation of one copy of Acvrl1 delayed tumor growth, while reducing the Eng gene dosage by half did not affect the growth rate of PanNET in RIP1-TAg2 mice." (PMID 27741515, 2016). "Interestingly, 12-week old compound RIP1-TAg2; Acvrl1+/−Eng+/− mice presented with a significantly reduced overall tumor burden by 57% and 39%, compared to RIP1-TAg2; Acvrl1+/+Eng+/+ mice or RIP1-TAg2; Acvrl1+/−Eng+/+ mice, respectively." (PMID 27741515, 2016). "The higher expression of ACVRL1 in KIRC and GBM tumors might reflect the architecture of the organs in which these cancers arise and develop, including a naturally strict dependency on the vasculature of these tumor types." (PMID 30132150, 2019). "In conclusion, expression of ACVRL1 is not simply coupled to established pathways such as angiogenesis, but is also extended to a regulatory network of processes that affect both malignant cells and other cellular entities of the tumor microenvironment, specifically immune cells." (PMID 30132150, 2019).
cancer (17 papers, 2014 to 2026). A tumor composed of atypical neoplastic, often pleomorphic cells that invade other tissues. "A 62-year-old Chinese man was diagnosed with HHT type 2 (harboring an ACVRL1 gene mutation) and Barcelona Clinic Liver Cancer (BCLC) stage B HCC." (PMID 41583846, 2025). "Here, we present data revealing the genetic network associated with ACVRL1 (the gene encoding for ALK1) expression in human cancer tissues." (PMID 30132150, 2019). "Here, we provide insights to the broader regulatory network associated with ACVRL1 expression in different human cancers." (PMID 30132150, 2019). "Moreover, the emergence of ACVRL1+ TAMs was associated with disease progression upon development of therapeutic resistance in cancer patients." (PMID 39808498, 2025). "In order to gain a broader understanding of the gene network linked to ACVRL1 in human cancers, a ranked list of ACVRL1-correlated genes was generated in the cBioPortal for cancer genomics and subjected to gene set enrichment analysis (GSEA), using the “hallmarks” collection as reference sets." (PMID 30132150, 2019). "Meanwhile, we identified GO- and KEGG-enriched signaling pathways associated with cancer-related transcriptional dysregulation, as well as biological processes involving endothelial cell proliferation, which are closely linked to the function of ACVRL-1 and its downstream signaling molecules." (PMID 41579221, 2026). "Similarly, Renca cells showed dynamic expression changes of multiple genes across passages, including Btbd17, Loxl3, Raf1, and Acvrl1, which may be closely associated with signal transduction, transcriptional regulation, and cancer-related pathways." (PMID 41272245, 2025). "Activin A receptor-like type 1 (ACVRL1) is a multifunctional signaling molecule that serves an important function in angiogenesis and cancer development." (PMID 40403492, 2025). "Our findings also impact on the wider role of ACVRL1 in regulating cardiovascular pathophysiology and the development of anti-ACVRL1 therapies for treating cancer patients." (PMID 24896812, 2014). "Notably, ACVRL1+ TAMs coincided with an immunosuppressive phenotype and were overrepresented in human cancers progressing on therapy." (PMID 39808498, 2025). "Among them, ACVRL1 is associated with the TGF-β pathway, which hampers antitumor immune response; Bcl-2 regulates the apoptosis pathway, which correlated inversely with TMB in four cancer types." (PMID 36911742, 2023). "In the context of cancer, we started off by generating and validating a TAM-specific ACVRL1 signature." (PMID 39808498, 2025).
vascular disorder (6 papers, 2016 to 2022). A general term used to describe any disease affecting blood vessels]. "Use of NGS-based gene panels including not only ENG, ACVRL1 and MADH4 but also RASA1 and EPHB4 genes, which are associated with the HHT-like syndrome accelerates the diagnosis of these hereditary vascular disorders." (PMID 33807613, 2021). "Mutations in Smad4, together with ACVRL1 (ALK1) and ENG are causative of the vascular disorder HHT." (PMID 30200294, 2018). "Moreover, other regionalized vascular disorders such as hereditary hemorrhagic telangiectasia (HHT) and pulmonary arterial hypertension (PAH) are mainly caused by mutations in the BMP receptors ACVRL1 (encoding ALK1) or ENG (encoding Endoglin) and BMPR2 respectively." (PMID 27724845, 2016).
heart disease (1 paper, 2025). "The other findings were pathogenic variants in genes causing severe heart disease (ACVRL1, PKP2 and SCN5A)." (PMID 40620702, 2025).
ACVRL1 also shares sentences with these, for which no sentence is quoted: pulmonary hypertension (9 papers); hereditary hemorrhagic telangiectasia type 2 (6); genetic disease (5); colorectal cancer (4); infection (3); glioma (2); hepatocellular carcinoma (2); Hereditary hemorrhagic telangiectasia types 1 (2); ischemic stroke (2); Pulmonary capillary hemangiomatosis (2); Alport syndrome (1); Alzheimer disease (1); atherosclerosis (1); autosomal dominant disease (1); Barth syndrome (1); basal cell carcinoma (1); breast (1); Breast Invasive Carcinoma (1); cerebral cavernous malformation (1); Cirrhosis (1); cognitive decline (1); colon cancer (1); connective tissue disease (1); dementia (1); diabetes (1); endometrial cancer (1); essential hypertension (1); gastric tumors (1); gastrointestinal polyp (1); glioblastoma multiforme (1).
A further 26 diseases each share a sentence with ACVRL1 in 1 paper.